IFITM3 (interferon induced transmembrane protein 3)
Diseases named in the same sentence as IFITM3 in open-access papers (continued):
Sharing a sentence is not in itself a finding about the gene and the disease.
cancer (continued). "Intriguingly, although part of an ISG signature, anti-cancer or anti-inflammatory roles are rarely attributed to IFITM3." (PMID 33364194, 2020). "Moving forward, many interesting avenues remain for pursuing IFITM3’s immunological and cancer roles." (PMID 33364194, 2020). "Interferon induced transmembrane protein (IFITM3) is highly expressed in cancers and is a marker of poor prognosis." (PMID 33364194, 2020). "Factors such as TGF- β, and IFNs, in the microenvironment, not only upregulate expression of IFITM3, but also contribute to upregulation of immunosuppressive molecules on both immune and cancer cells, facilitating immune escape." (PMID 33364194, 2020). "Conversely, another report suggests IFITM3 plays a crucial role in paracrine senescence via small extracellular vesicles, which are important in cancer treatment." (PMID 33364194, 2020). "Recently, the involvement of IFITM3 in cancer was further extended to include spatial regulation of the Src oncoprotein." (PMID 29162141, 2017). "IFITM3 is over expressed in different types of cancers, such as breast, promoting epithelial-mesenchymal transition through the Wnt/β-catenin signaling." (PMID 26446766, 2015). "Upregulation of other cancer-associated genes in MPOSE – such as Ccnd1, Btc, Ankrd1, Oraov1, Cd44 and Ifitm3 – as well as possible DNA mutations or fusions, may also contribute to tumorigenic differences and warrant further investigation." (PMID 40642792, 2025). "Overexpression of IFITM3 has been reported to induce autophagy in some cancer cell lines." (PMID 38668245, 2024). "IFNγ is one of the main mediators of inflammation in cancer and development of an IFNγ signaling score led to the identification of IFITM3 as both a prognostic biomarker and a direct target of IFNγ with a potential dependency in AML cells lines, i.e., its deletion led to loss of AML cell fitness." (PMID 38418901, 2024). "Moreover, IFITM3 is also overexpressed in multiple types of cancer cells, and its expression correlates with histopathological grading and staging." (PMID 38167862, 2024). "In view of the observation that IFITM3 was involved in chemoresistance, we continued to ascertain whether the function of IFITM3 in mediating cancer stemness contributed to the 5’FU and cisplatin chemoresistance in GC." (PMID 35941699, 2022). "In addition to MCM2 to MCM7, six downstream oncogenic targets of c-MYC implicated in cancer survival and metabolism including PSMA1, PSMA6, PSMB2, HDAC2, LDHA and SPRING were positively correlated with IFITM3 in 71 GC specimens using the Cho dataset." (PMID 35941699, 2022). "In addition to the widely studied antiviral function of the IFITMs, IFITM1 and IFITM3 also function as a pro-oncogenic protein for which the expression has been reported in various cancers such as breast, cervix, colon, leukemia, ovary, brain, and esophagus." (PMID 36008984, 2022). "IFITM3 is involved in multiple pathologies including cancer and Alzheimer27,28." (PMID 36153346, 2022). "In conclusion, IFITM3 expression can be used to identify immuno-hot tumors in most cancers, and IFITM3 may be a promising pancancer biomarker to estimate the immunological features of tumors." (PMID 34456915, 2021). "Taken together, IFITM3 is a pancancer biomarker for identifying immunogenicity in human cancers." (PMID 34456915, 2021). "In addition to BLCA, IFITM3 is expected to be a marker of high immunogenicity in most human cancers." (PMID 34456915, 2021). "The prognostic value of IFITM3 in human cancers was limited." (PMID 34456915, 2021). "Moreover, the pancancer analysis suggests that IFITM3 is an identifying factor for high immunogenicity in most cancers." (PMID 34456915, 2021). "Among these members, the role of IFITM3 in cancer is becoming apparent similarly as IFITM1." (PMID 32668617, 2020). "Furthermore, IFITM3 overexpression increases cell proliferation, migration and invasion, all of which are hallmarks of cancer." (PMID 33364194, 2020).
cancer (continued). "Therefore, the overall effect of high IFITM3 expression appears to be cancer progression and poor survival." (PMID 33364194, 2020). "We next examined the prognostic survival of TMPRSS2 and IFITM3 in patients with cancers by ENCORI." (PMID 33061814, 2020). "IFITM3 appears to also play a crucial role in cancer cell division and migration." (PMID 33364194, 2020). "The role of IFITM3 in cancer is being increasingly scrutinized." (PMID 33364194, 2020). "Furthermore, IFITM3 suppresses IL-6 production, a pro-inflammatory cytokine required for cancer cell migration and invasion." (PMID 33364194, 2020). "Collectively, the twin antiviral proteins IFITM2 and IFITM3 may serve as biomarkers for tumorigenic phenotypes as well as targets for anti-cancer interventions." (PMID 29162141, 2017). "Moreover, IFITM1 and IFITM3 confer a sphere-forming ability to various cancers." (PMID 36466909, 2022). "However, the expression status of IFITM3 was inconsistent in most cancers." (PMID 34456915, 2021). "Thus, IFITM3 may function as a friend or foe in cancer, and understanding this balancing act may be an interesting hotspot for further research." (PMID 34456915, 2021). "Therefore, it is possible that IFNs in the TME drive IFITM3 expression in cancer and stromal cells." (PMID 33364194, 2020). "Furthermore, IFITM3 plays a key role in cancer growth and maintenance." (PMID 33364194, 2020). "However, the clinical significance and underlying mechanisms of dysregulated IFITM3 expression in cancers are still not well defined." (PMID 33364194, 2020). "Therefore, it is important to understand how IFITM3 expression is dysregulated in cancer." (PMID 33364194, 2020). "Therefore, targeting of IFITM3 will likely have implications for potential cancer therapies." (PMID 33364194, 2020). "Moreover, IFITM3 was detected in endothelial cells and several cancer cell-derived sEVs by MS." (PMID 31665090, 2019). "However, the role of IFITM3 in cancer is still poorly understood." (PMID 24370119, 2013). "IFITM3 and GBP5 both act as downstream factors of the IFN-γ/STAT1 pathway and can serve as cancer biomarkers." (PMID 40909948, 2025). "We further calculated Spearman correlations between IFITM3 expression and MHC-I scores across cancer types and observed a consistent inverse relationship between the average MHC-I score and the strength of this correlation." (PMID 40611157, 2025). "IFIT1 affects cancer cell behavior through Wnt/β-Catenin signaling, and IFITM1, IFITM2, and IFITM3 are related to antiviral functions." (PMID 38424218, 2024). "Thus, the roles of IFITMs in cancer (discussed in detail in the following section) may also be fruitfully viewed in the light of the immunoregulatory actions of these proteins, thus far only investigated closely for IFITM3." (PMID 36435199, 2023). "We next examined how overexpression of WT ENPP1 in cancer cells affected STING activation in cGAMP responder cells as measured by their combined Ifitm1, Ifitm2, and Ifitm3 expression (Ifitms)." (PMID 38117852, 2023). "Overexpression of IFITM3 in GC cancers was also observed in another independent cohort of patients (Cho, GSE13861) as relative expression of IFITM3 was significantly higher in micro-dissected GC tissues as compared to adjacent normal gastric tissues." (PMID 35941699, 2022). "Specifically, we discovered that IFITM3 was positively correlated with the expression of critical immunomodulators, such as CCL5, CXCL9, and CXCL10, as well as the activities of the cancer-immunity cycle." (PMID 34456915, 2021). "In the TCGA database, most types of cancer expressed higher IFITM3, while in CHOL, MESO, and several other cancers, IFITM3 exhibited low expression." (PMID 34456915, 2021). "More importantly, IFITM3 expression was positively related to immunomodulator (including chemokine, MHC, immunostimulator, and receptor) and TIIC levels across cancers." (PMID 34456915, 2021).
cancer (continued). "Interestingly, the expression levels of Ifitm2 and Ifitm3, pivotal players in cellular antiviral defense, were elevated in PMN-MDSCs derived from cancer patients." (PMID 38919617, 2024). "Notably, genetic KO of IFITM1 and IFITM3 inhibited the synthesis of a subset of IFN-responsive proteins, which is consistent with the notion of an immunoregulatory role for IFITMs in cancer." (PMID 36435199, 2023). "Nonetheless, the molecular mechanism whereby IFITM1 and IFITM3 proteins regulate cancer is not well defined." (PMID 36008984, 2022). "Seven TEPs mRNAs were discovered in our study: RSL24D1, IFI27, CRYM, HBD, IFITM3, FCGR2A, and KLHDC8B in TEPs, which are mainly enriched in protein binding, extracellular matrix, and metabolic process, and may be used for cancer diagnosis." (PMID 33955587, 2021). "Consequently, we believe alternative TEPs mRNAs, including RSL24D1, IFI27, CRYM, HBD, IFITM3, FCGR2A, and KLHDC8B mRNA, can potentially serve as non‐invasive biomarkers for diagnosing cancers and can even predict the prognosis of pan‐cancer." (PMID 33955587, 2021). "The RNA level of IFITM3 was markedly upregulated in cancer tissues compared with corresponding noncancer adjacent hepatic tissues (P = 0.038)." (PMID 33816616, 2021). "In this study, 7 TEPs mRNAs were verified, including RSL24D1, IFI27, CRYM, HBD, IFITM3, FCGR2A, and KLHDC8B, which may be used for cancer detection." (PMID 33955587, 2021). "While IFITM3 localization in cancer cells has not yet been well described, IFITM3 appears to be localized both in the cytosol and the nucleus." (PMID 33364194, 2020). "Overall, these data imply a novel role for the autophagic protein Ambra1, and its key interacting partners Dynactin 1 and IFITM3, at the heart of an intracellular trafficking network that, in turn, acts as a ‘spatial rheostat’ for phospho-Src and Src/FAK-mediated cancer processes." (PMID 28362576, 2017). "These evidences suggest that IFITM3 might not be an indispensable factor in stemness maintenance of cancer cells, despite the close correlation between protein expression and stemness status." (PMID 38218875, 2024). "In present study, we reported that IFITM3 served as a novel modulator of HGF/MET-mediated AKT signaling that suppressed FOXO3 (Forkhead Box O3), consequently leading to c-MYC (MYC proto-oncogene) mediated cancer proliferation, migration, stemness and drug resistance." (PMID 35941699, 2022). "The IFITM1, IFITM2 and IFITM3 proteins influence the epithelial–mesenchymal transition (EMT) status, cell migration, invasion and the presence of distant metastases, as has been shown in both in vitro and in vivo studies performed with various cancer cell lines, animal models and patient samples." (PMID 36466909, 2022). "Therefore, if IFITM3 is an intermediate in TGF-β signaling, IFITM3 may also unite these two cancer-related pathways." (PMID 33364194, 2020). "After subcutaneous injection, 100 Ifitm3+ germ cell-like cells sorted from various cancer cell lines could all give rise to tumors, and some of which exhibited high level of mature tissues, especially in those from the PC3 cancer cell line." (PMID 30302273, 2018). "Therefore, we suggested that IFITM3 could be used as an indicator of the susceptibility of SARS-CoV-2, not just ACE2 and TMPRSS2 in cancer patients." (PMID 33061814, 2020).
neurodegenerative disease (5 papers, 2015 to 2022). A disorder of the central nervous system characterized by gradual and progressive loss of neural tissue and neurologic function. "The requirement for BIN1 to regulate Ifitm3 upregulation during inflammation has important implications for inflammatory responses during the pathogenesis and progression of many neurodegenerative diseases." (PMID 35526014, 2022). "Future studies will be required to clarify whether IFITM3 has the capacity to modulate microglial phenotype versus whether it is induced as a result of microglial phenotypical change in conditions of neurodegenerative diseases." (PMID 36012150, 2022). "In general, endothelial CD147 deficiency reduces the expression of core AD genes, including App, Psen2, and Ifitm3, and we hypothesize that CD147 is a promising risk factor for AD and other neurodegenerative diseases." (PMID 33987940, 2021). "Besides being reported in neurodegenerative diseases, Ifitm3 also has been shown to respond to Poly I:C as an inducer of type I interferons, by increasing gene expression in astrocytes." (PMID 25856311, 2015).
bacterial infection (3 papers, 2013 to 2024). "Additionally, EVs from severe patients isolated by CD9+ immunocapture and mS1-EVs trapping showed increased amounts of IFITM3, an antiviral response protein previously associated with EVs in other viral and bacterial infections." (PMID 39569406, 2024).
psychiatric disorder (3 papers, 2018 to 2023). A disorder characterized by behavioral and/or psychological abnormalities, often accompanied by physical symptoms. "Although IFITM3 is increased in the brains of patients with neurological and psychiatric disorders, its role in the central nervous system is largely unknown." (PMID 37602193, 2023). "Taken together with our present findings, it is possible that Fstl1 may play a role in the pathophysiology of psychiatric disorders on downstream of Ifitm3." (PMID 30348171, 2018).
neurological disease (2 papers, 2020 to 2022). "Finally, we summarize several ISGs (ISG15, IFIT2, IFITM3) that have been studied more in recent years for their antiviral infection in the CNS and their research progress in neurological diseases." (PMID 36325336, 2022). "In addition, substantial progress has been made in our understanding of individual ISGs (ISG15, IFIT2, IFITM3) in CNS viral infection and diseases in recent years, providing an essential target for the development of novel antivirals and anti-neurological disease drugs." (PMID 36325336, 2022). "Since the GxxxG motif is a shared feature of IFITM3 and PRRT2 and that a naturally occurring mutant G305W is predictive of neurological disease, we assessed the oligomerization capacity of WT and mutant PRRT2." (PMID 33112230, 2020).
brain disease (1 paper, 2020). "Furthermore, five out of the 12 RG‐specific proteins (COL11A1, RRAS, GLUD1, IFITM3, and MGST1) are involved in human epileptic disorders prompting the hypothesis that modification of the extracellular environment is a common feature in this type of brain disease." (PMID 32378798, 2020).
central nervous system diseases (1 paper, 2023). "However, the mechanism of action of IFITM3 in immune activation-related central nervous system diseases still needs more in-depth research." (PMID 37602193, 2023).
colon (1 paper, 2018). "Furthermore, the results of a more recent studyindicated elevated IFITM3 expression in colon cancercells compared to normal colon cells." (PMID 30983867, 2018).
immune diseases (1 paper, 2025). "It has been confirmed that IFITM3 can interact with γ-secretase in AD, but whether γ-secretase is also involved in other immune diseases with IFITM3 remains to be confirmed." (PMID 40927393, 2025).
lymph node (1 paper, 2015). "Through thorough follow-up, a total of 42 cases (40.4%) were confirmed to have first lymph node metastatic recurrence within 3 years, in which IFITM3 overexpression was detected in 30 patients (71.4%)." (PMID 26539332, 2015).
neurodevelopmental disorder (1 paper, 2015). A behavioral and cognitive disorder with onset during the developmental period that involves impaired or aberrant development of intellectual, motor, or social functions. "Together, type I IFN-signaling cascades to induce IFITM3 and IL-6 may be possible targets for neurodevelopmental disorders triggered by perinatal immune activation." (PMID 26633355, 2015).
respiratory disease (1 paper, 2016). "Our results show that the IFITM3 rs12252 variant was associated with respiratory disease hospitalizations but not in the ILI patients with a laboratory confirmed Influenza A(H1N1)pdm09 infection." (PMID 27351739, 2016).
IFITM3 also shares sentences with these, for which no sentence is quoted: viral disease (11 papers); Azoospermia (2); colon adenocarcinoma (2); Ebola (2); Encephalopathy (2); Hypercholesterolemia (2); infectious disease (2); leukemia (2); pneumonia (2); sarcoidosis (2); type 2 diabetes (2); acute lymphoblastic leukemia (1); arenavirus infection (1); astrocytoma (1); autoimmune disease (1); autoimmune myocarditis (1); B-cell acute lymphoblastic leukemia (1); B-cell lymphomas (1); blastomycosis (1); bovine respiratory disease complex (1); brain tumor (1); bronchitis (1); colonic adenomas (1); colorectal tumors (1); disc degeneration (1); encephalitis (1); hematological malignancies (1); hemorrhagic fever (1); hepatitis C virus infection (1); inflammation (1).
A further 19 diseases each share a sentence with IFITM3 in 1 paper.